CST4 (cystatin S)
Diseases named in the same sentence as CST4 in open-access papers:
CST4 is named in the same sentence as 74 diseases in open-access papers, as found by Europe PMC text mining. Sharing a sentence is not in itself a finding about the gene and the disease. The quoted sentences say what the papers report.
colorectal cancer (5 papers, 2017 to 2025). A primary or metastatic malignant neoplasm that affects the colon or rectum. "Recent studies also indicated CST4 was a novel and improved diagnostic marker for colorectal cancer." (PMID 37978366, 2023). "For example, the salivary cystatins CST1, CST2, CST3, and CST4 were associated with both local invasion at the early stage and remote metastasis in colorectal cancer." (PMID 28523467, 2017). "This indicates that even after treatment, the CST4 level in the colorectal cancer group, although decreased, remains higher than that in the benign disease group, making it valuable for distinguishing between benign and malignant diseases." (PMID 41040534, 2025). "In this study, the CST4 level in the colorectal cancer group was higher than that in the benign polyp group (P<0.05)." (PMID 41040534, 2025). "The combination of serum CST4 and DR-70 was reported to further enhance the diagnosis of early colorectal cancer." (PMID 37978366, 2023). "Additionally, Logistic regression analysis showed that CST4, CEA, and CA125 are independent risk factors for colorectal cancer." (PMID 41040534, 2025). "Data on the correlation between CST4 and colorectal cancer (CRC) metastasis are scarce." (PMID 34194498, 2021). "The overexpression of CST4 in gastrointestinal cancer tissues and cell lines was validated as exhibiting high specificity and sensitivity, indicating that it might be a novel blood biomarker for gastric and colorectal cancer." (PMID 34194498, 2021). "To functionally validate the regulatory relationship between CST4 and PDGFRB suggested by bioinformatic analyses, we performed in vitro knockdown experiments in HCT116 colorectal cancer cells." (PMID 41040534, 2025). "Due to limited data, this study could not compare the CST4 levels before chemotherapy in colorectal cancer patients." (PMID 41040534, 2025).
gastric cancer (5 papers, 2021 to 2025). A primary or metastatic malignant neoplasm involving the stomach. "Studies have shown that CST4 is closely related to breast cancer, esophageal cancer, and gastric cancer." (PMID 41040534, 2025). "The uniform CST4 expression across metastatic subgroups aligns with recent findings in gastric cancer surveillance, where treatment-induced biomarker dynamics often override initial tumor characteristics." (PMID 41040534, 2025). "ELFN2 is a vital postsynaptic adhesion molecule in brain behaviour and ELFN2 signalling pathway also acts as the downstream molecule of CST4, which promoted aggressiveness in gastric cancer." (PMID 35685372, 2022). "Previous studies have shown that not only is CST4 markedly upregulated in gastric cancer tissues, but its overexpression also significantly promotes the proliferation, migration, and invasion of gastric cancer cells." (PMID 34194498, 2021). "However, CST4 shows a high expression in gastrointestinal cancer cells and tissues; and in gastric cancer study, CST4 upregulation contributes to the gastric carcinogenesis and progression by modulating NLFN2 signaling pathway." (PMID 35440286, 2022). "In contrast to previous reports of CST4 and CST5 being upregulated in gastric cancer tissue and serum, our study found both proteins to be significantly downregulated in saliva samples from GC patients." (PMID 41164825, 2025). "Our findings demonstrate that salivary proteins, particularly S100A8, S100A9, CST4, and CST5, hold significant potential as non-invasive biomarkers for gastric cancer detection." (PMID 41164825, 2025). "In this study, we used iTRAQ and PRM-based quantitative proteomics to detect four saliva protein biomarkers of gastric cancer, including S100A8, S100A9, NUCB2, and CST4, which make them potential novel biomarkers for the noninvasive diagnosis of GC." (PMID 41164825, 2025).
gingivitis (5 papers, 2008 to 2025). A disorder involving inflammation of the gums; may affect surrounding and supporting structures of the teeth. "A recent study showed an underrepresentation of cysteine endopeptidase inhibitor activity in healthy pregnant women and pregnant women with gingivitis (mediated by type-2 cystatins, mainly Cystatin-S, -SA, and -SN)." (PMID 36355174, 2022).
cyst (3 papers, 2020). A sac-like closed membranous structure that may be empty or contain fluid or amorphous material. "IFA showed that cyst wall proteins CST4, CST8, CST9, and MCP3 were successfully knocked out and complemented back." (PMID 32019789, 2020). "The major cyst wall glycoprotein CST1, at least 22 dense granule (GRA) proteins, and other proteins, including CST4, BPK1, MAG1, MCP3, MCP4, and MYR1, were identified in the cyst wall/membrane of in vitro cysts." (PMID 32132158, 2020). "Studies on T. gondii AP2 transcription factors revealed that the expression of CST4 and MCP3, among other cyst wall and cyst matrix proteins such as BPK1, MCP4, and MAG2, was altered when the AP2 bradyzoite activators and repressors were disrupted." (PMID 32019789, 2020). "This analysis yielded an inventory of previously undescribed cyst wall proteins (CST2/GRA50, CST3/GRA51, CST4, CST5/GRA52, and CST6/GRA53) that were validated to localize to the cyst wall by immunofluorescence." (PMID 32019789, 2020). "CST4 and MCP3 are among several cyst wall and matrix proteins that have their expression regulated during bradyzoite differentiation, directly or indirectly through AP2 transcription factors." (PMID 32019789, 2020). "After generating the deletion and complementation strains for CST4, CST8, CST9, and MCP3, these parasites were assayed for parasite and cyst biology." (PMID 32019789, 2020). "We also detected differential phosphorylation of the cyst wall proteins CST1, CST3, CST4, and CST6." (PMID 32907954, 2020). "Since only CST2-BirA*, CST4-BirA*, CST9-BirA*, and MCP3-BirA* parasites showed biotin ligase activity at the cyst wall, streptavidin affinity capture of the potential interacting partners of these cyst wall strains was performed and processed by LC-MS/MS." (PMID 32019789, 2020). "Betweenness analysis, which shows the importance of a node in connecting the different clusters together, suggests the data from the CST4-BirA* and GRA6-BirA* pulldowns are most important in structuring the three distinct clusters seen within the cyst wall interactome model." (PMID 32019789, 2020). "While CST4, CST8, and CST9 do not seem to play a role in determining cyst size, a lack of MCP3 resulted in statistically smaller cysts." (PMID 32019789, 2020). "When no exogenous biotin was provided, CST2-BirA*, CST4-BirA*, CST9-BirA*, and MCP3-BirA* strains showed no increase in streptavidin signal at the cyst wall." (PMID 32019789, 2020).
dry eye (3 papers, 2015 to 2025). "For instance, LCN1, PIP, LTF, and SG2A1 were substantially reduced in dry eye, while AZGP1, LEG7, CST4, CST1, and ACTB were diminished in MGD." (PMID 35685417, 2022). "Different proteins involved with dry eye dysfunction: ANXA1, ANXA11, CST4, PRDX5, PLAA and S100A6; were validated as biomarkers." (PMID 26287192, 2015). "CST4 and SMR3B are considered as potential dry eye biomarkers." (PMID 40700273, 2025).
asthma (2 papers, 2011 to 2022). "A recent study found 5 hub genes (SERPINB2, SERPINB4, LTF, MUC5B, and CST4) related to the pathogenesis of asthma in bronchial and nasal cells." (PMID 36076228, 2022).
blepharitis (2 papers, 2013 to 2023). Inflammation of the eyelids near the eyelashes. "CST4 concentration in tears have been registered in patients with ADDE, blepharitis, Fusarium keratitis and MGD." (PMID 37185712, 2023).
dental caries (2 papers, 2018 to 2021). The decay of a tooth, in which it becomes softened, discolored, and/or porous. "This study confirms the association between cystatin S protein and dental caries in children aged 48–71 months." (PMID 34922509, 2021). "They concluded that the level of cystatin S in dental pellicle in CF individuals was higher than dental caries ones." (PMID 34922509, 2021). "They revealed that cystatin S level in CF group was higher than the dental caries group." (PMID 34922509, 2021). "In our previous study, the STRING online database, we identified 63 interactions in saliva samples from children with and without dental caries, and reported associations among histatin-1, mucin-5B, mucin-7, and cystatin S." (PMID 30359274, 2018).
fungal keratitis (2 papers, 2008 to 2013). "We have shown earlier variation in the expression level of tear proteins (prolactin inducible protein, serum albumin precursor, cystatin S precursor, cystatin SN precursor, cystatin, and human tear lipocalin) in fungal keratitis patients." (PMID 23308132, 2013).
ovarian carcinoma (2 papers, 2022 to 2023). A malignant neoplasm originating from the surface ovarian epithelium. "In addition, CST4 can also remodel tumor microenvironment in ovarian cancer, and high CST4 expression is associated with the dismal survival of ovarian cancer patients." (PMID 35440286, 2022).
autoimmune conditions (1 paper, 2015). "Similar findings were reported in a human tears study, which demonstrated increase in cystatin S and lactotransferrin levels in tears collected from patients with autoimmune conditions." (PMID 26779447, 2015).
bacterial vaginosis (1 paper, 2020). Infection caused by bacterial overgrowth in the vagina. "In contrast, CST4-7 had higher relative abundances of unclassified Clostridiales, unclassified Clostridiales Family XI, unclassified phyla, and bacterial vaginosis (BV)-associated bacteria like Prevotella and Porphyromonas." (PMID 32850898, 2020).
bladder cancer (1 paper, 2022). "Bioinformatic database screening for bladder cancer followed by gene co-expression network analysis revealed six new genes (PPARD, CST4, CSNK1E, PTPN14, ETV6, and ADRM1) and several new miRNAs, including miR-124, as drivers in the development and progression of bladder cancer." (PMID 36362406, 2022).
chronic kidney disease (1 paper, 2019). Impairment of the renal function secondary to chronic kidney damage persisting for three or more months. "For instance, rs911119 located in the CST3/CST4/CST9 gene cluster was reported previously associated with chronic kidney disease in a European population." (PMID 30704471, 2019).
endometrial carcinoma (1 paper, 2025). A malignant tumor arising from the epithelium that lines the cavity of the uterine body. "The diversity increased greatly from benign to high-grade endometrial carcinoma and the benign condition, low-grade endometrial carcinoma and high-grade clustered into CST1, CST 2, and both CST3 and CST4, respectively." (PMID 40041148, 2025).
gastric adenocarcinoma (1 paper, 2021). "The expression of CST4 was examined in cancer tissues and their corresponding adjacent normal tissues from 40 gastric adenocarcinoma patients." (PMID 34194498, 2021).
intestinal tumor (1 paper, 2025). "Gastric and intestinal tumor cells secrete CST4, which is transported to the blood, so the detection of serum CST4 has been well-defined as conducive to diagnosing some malignancies, mainly gastrointestinal tumors." (PMID 41164825, 2025).
lung carcinoma (1 paper, 2022). "We picked the top 5 genes (ZNF24, NR3C2, CST4, ARHGDIG and CRYBB3) to confirm their lung cancer suppressive function." (PMID 36457047, 2022).
Obesity (1 paper, 2022). Accumulation of substantial excess body fat. "When compared to OWP, pregnant women with obesity and periodontitis showed a down-regulation of Cystatin-S, -SA, -SN, -B, and -D, while Cystatin-C was up-regulated." (PMID 36355174, 2022).
periodontal disease (1 paper, 2023). "CST4 has been reported to exert an antibacterial effect on Porphyromonas gingivalis, which is involved in periodontal disease." (PMID 37193030, 2023).
polyp (1 paper, 2025). A usually exophytic mass attached to the underlying tissue by a broad base or a thin stalk. "CRC patients exhibited significantly elevated CST4 levels compared to polyp controls (median [IQR]: 54.07 [32.18-91.49] vs 37.48 [24.18-49.28] U/mL, P<0.05)." (PMID 41040534, 2025). "Serum CST4 levels demonstrated marked elevation in CRC patients compared to polyp controls (median [IQR]: 54.07 [32.18–91.49] U/mL vs. 37.48 [24.18–49.28] U/mL; P < 0.01)." (PMID 41040534, 2025).
thyroid carcinoma (1 paper, 2021). "In this study, we presented the data that ENO1 positively regulated the expression of CST1 and CST4 in thyroid carcinoma cells." (PMID 33968941, 2021). "There was a positive correlation between ENO1 and CST1/CST4 in human thyroid carcinoma tissues." (PMID 33968941, 2021). "Next, we studied the role of CST1 and CST4 in thyroid carcinoma." (PMID 33968941, 2021). "Functional experiments demonstrated that knockdown of CST1, but not CST4, suppressed the growth of growth of thyroid carcinoma cells." (PMID 33968941, 2021).
thyroid- (1 paper, 2022). "At the same time, a study of thyroid-associated orbitopathy revealed cystatin-C (CST4) among the top upregulated proteins, as we observed it for patients with CRVO among numerous defending proteins." (PMID 36498980, 2022).
cancer (24 papers, 2010 to 2025). A tumor composed of atypical neoplastic, often pleomorphic cells that invade other tissues. "The KM survival curves showed that CST5 and CST4 were risk factors, and high CST5 and CST4 levels in cancer tissue were associated with worse PFS, compared with the low-risk group (P < 0.05)." (PMID 41164825, 2025). "Cystatin SA (CST2) and Cystatin S (CST4) are known to be present in seminal fluid, have anti-viral properties and elevated levels have been reported for many cancer types including PCa39–41." (PMID 41258098, 2025). "Nomograms were drawn based on CST2 and CST4 expression levels, age, tumor stage, cancer status, residual tumor, and targeted therapy." (PMID 37978366, 2023). "IHC staining showed that CST4 staining in cancer tissue was stronger than that in paracancerous tissue." (PMID 34194498, 2021). "The expression level of CST4 in specimens (cancer and normal tissues) was assessed through immunohistochemistry and/or quantitative polymerase chain reaction." (PMID 34194498, 2021). "Additionally, CST4/CST5 may be consumed or degraded more rapidly in the oral cavity environment of cancer patients due to shifts in oral microbiota or protease activity." (PMID 41164825, 2025). "We selected eight candidates (CST4, CCL20, CX3CL1, CXCL5, CXCL8, GDF15, CCL5 and MMP3) that play an important role in cancer pathogenesis for further study." (PMID 38385965, 2024). "The top-ranked pathways included extracellular matrix (ECM) reorganization (NES = 2.12, FDR q<0.001), focal adhesion signaling (NES = 1.98, FDR q=0.004), and cancer-related pathway activation (NES = 1.85, FDR q=0.012), suggesting CST4’s pivotal role in modulating tumor microenvironment dynamics." (PMID 41040534, 2025). "For examples, RSAD2, involved in antiviral defense, has not been reported as being related to cancer, as well as SGPP2, known to be involved in pro-inflammatory signaling, and CST4." (PMID 21060876, 2010).
tumor (18 papers, 2004 to 2025). "Our findings demonstrate that CST4 maintains stable discriminative capacity across tumor stages and age groups, achieving superior diagnostic performance compared to conventional markers like CEA." (PMID 41040534, 2025). "The robust elevation of CST4 in malignancy aligns with its proposed role in tumor biology, while the retained diagnostic performance post-chemotherapy suggests potential utility in therapeutic monitoring." (PMID 41040534, 2025). "Elevated CST4 expression has been mechanistically linked to tumor progression in breast and gastric carcinomas." (PMID 41040534, 2025). "Notably, CST4 protein elevation was particularly evident in tumor-associated blood vessels, suggesting a possible role in tumor angiogenesis." (PMID 41040534, 2025). "Notably, CST4 maintained diagnostic independence across tumor stages (P>0.05) and age groups." (PMID 41040534, 2025). "Quantitative histoscore analysis revealed 4.7-fold higher PDGFRB expression in tumor vasculature (P<0.001), aligning with CST4’s observed pro-angiogenic effects." (PMID 41040534, 2025). "Serum CST4 levels were quantified by ELISA alongside six conventional tumor markers (CEA, CA125, CA153, CA199, AFP, CA724)." (PMID 41040534, 2025). "In CRC biology, preliminary proteomic studies have identified CST4 overexpression in tumor tissues compared to adjacent normal mucosa, suggesting its potential involvement in lymphatic invasion processes." (PMID 41040534, 2025). "Previous studies have reported that cystatins (CST4) were involved in tumor invasion and metastasis." (PMID 35393513, 2022). "To establish the clinical utility of CST4 in post-chemotherapy CRC surveillance, we performed receiver operating characteristic (ROC) analysis comparing its diagnostic performance against conventional tumor markers." (PMID 41040534, 2025). "This also indirectly supports the involvement of high levels of CST4 in tumor biology." (PMID 41040534, 2025). "Our findings suggest that CST4 could serve as a tumor marker that affects the prognosis of GC and could be considered as a potential therapeutic target for GC." (PMID 37978366, 2023). "In the tumors with circ_0023984 knockdown, the positive staining signals of Ki-67 and CST4 were largely reduced as compared to the tumor expressing sh-NC; while in tumors with circ_0023984 knockdown and CST4 overexpression, the level of Ki-67 and CST4 was partially increased." (PMID 35440286, 2022). "We also performed IHC staining of Ki-67 and CST4 in the xenograft tumor sections." (PMID 35440286, 2022). "Furthermore, the additive value of combining CST4 with established tumor markers in diagnostic algorithms has not been systematically investigated." (PMID 41040534, 2025). "One possible explanation is that CST4 and CST5, both members of the cystatin family, are expressed and regulated differently in salivary glands compared to tumor cells or blood components." (PMID 41164825, 2025). "Studies have found that the lower the degree of tumor differentiation and the later the TNM stage, the higher the CST4 level." (PMID 41040534, 2025). "This validates the CST4-PDGFRB axis as a key signaling pathway involved in extracellular matrix remodeling and tumor progression, offering novel insights into CRC pathogenesis." (PMID 41040534, 2025). "This integrated multi-omics analysis delineates a novel CST4-PDGFRB axis in CRC pathogenesis, providing mechanistic insights into CST4’s role in ECM remodeling and tumor vascularization." (PMID 41040534, 2025). "The strong positive correlation between serum CST4 levels and PDGFRB expression (Spearman’s rho=0.42, P<0.001) suggests a coordinated regulatory mechanism that may drive extracellular matrix (ECM) remodeling and tumor vascularization." (PMID 41040534, 2025).
gastrointestinal tumor (2 papers, 2025). "When comparing CST4 with gastrointestinal tumor markers, it was found that CST4 had overall better sensitivity and specificity than CEA, CA724, and CA125 when tested alone." (PMID 41040534, 2025).
CST4 also shares sentences with these, for which no sentence is quoted: infection (15 papers); viral infections (4); breast carcinoma (3); periodontitis (3); Alzheimer disease (2); colitis (2); COVID-19 (2); diabetes (2); fungal infection (2); head and neck cancer (2); psoriasis (2); allergic disease (1); amyloidosis (1); Anosmia (1); Arthritis (1); bacterial infection (1); cerebral small vessel disease (1); Chagas disease (1); cholestasis (1); coinfection (1); esophageal cancer (1); eye disorder (1); eye tumor (1); fascioliasis (1); fish disease (1); glaucoma (1); glomerular disease (1); hepatocellular carcinoma (1); Hyperglycemia (1); intestinal inflammation (1).
A further 18 diseases each share a sentence with CST4 in 1 paper.